COX8A (cytochrome c oxidase subunit 8A)
Description:
Component of the cytochrome c oxidase, the last enzyme in the mitochondrial electron transport chain which drives oxidative phosphorylation. The respiratory chain contains 3 multisubunit complexes succinate dehydrogenase (complex II, CII), ubiquinol-cytochrome c oxidoreductase (cytochrome b-c1 complex, complex III, CIII) and cytochrome c oxidase (complex IV, CIV), that cooperate to transfer electrons derived from NADH and succinate to molecular oxygen, creating an electrochemical gradient over the inner membrane that drives transmembrane transport and the ATP synthase. Cytochrome c oxidase is the component of the respiratory chain that catalyzes the reduction of oxygen to water. Electrons originating from reduced cytochrome c in the intermembrane space (IMS) are transferred via the dinuclear copper A center (CU(A)) of subunit 2 and heme A of subunit 1 to the active site in subunit 1, a binuclear center (BNC) formed by heme A3 and copper B (CU(B)). The BNC reduces molecular oxygen to 2 water molecules using 4 electrons from cytochrome c in the IMS and 4 protons from the mitochondrial matrix.
Synonyms: COX8; COX8L; COX8-2; VIII-L; COX; VIII; MC4DN15
Tractability: Small molecule: a structure with a bound ligand is known. Antibody: UniProt predicts a signal peptide or a membrane-spanning region. PROTAC: UniProt records ubiquitination sites on it.
Gene: Protein-coding gene on chromosome 11 (63,974,620 to 63,976,543, forward strand). Ensembl gene ENSG00000176340.
Subcellular location: Mitochondrion inner membrane
Pathways (Reactome):
Metabolism: Complex IV assembly; Respiratory electron transport
Cellular responses to stimuli: Cytoprotection by HMOX1
Gene Ontology:
Molecular function: protein binding; cytochrome-c oxidase activity
Biological process: cellular respiration; generation of precursor metabolites and energy; mitochondrial electron transport, cytochrome c to oxygen; oxidative phosphorylation; proton transmembrane transport; skeletal muscle tissue regeneration
Cellular component: mitochondrial inner membrane; mitochondrial membrane; mitochondrion; respiratory chain complex IV
Genetic constraint (gnomAD): Loss-of-function variants: 7 observed, 4.91 expected, observed/expected ratio (o/e) 1.42, 90% interval 0.76 to 1.92. That is too few expected variants to judge how well the gene tolerates losing a copy. Missense variants: 72 observed, 91.38 expected, observed/expected ratio (o/e) 0.79, 90% interval 0.65 to 0.96. Synonymous variants: 53 observed, 50.18 expected, observed/expected ratio (o/e) 1.06, 90% interval 0.85 to 1.33.
Gene-disease validity (ClinGen):
ClinGen rates the evidence that COX8A causes each of these diseases.
Leigh syndrome (autosomal recessive): Limited. A progressive neurological disease defined by specific neuropathological features associating brainstem and basal ganglia lesions.
mitochondrial disease (autosomal recessive): Limited.
Homologues: Orthologues: chimpanzee COX8A (99% identical), macaque COX8A (81% identical), rabbit COX8A (71% identical), guinea pig COX8A (68% identical), mouse Cox8a (68% identical), pig COX8A (67% identical), rat Cox8a (67% identical), zebrafish cox8a (32% identical). Paralogues in human: COX8C (32% identical).
Diseases named in the same sentence as COX8A in open-access papers:
COX8A is named in the same sentence as 49 diseases in open-access papers, as found by Europe PMC text mining. Sharing a sentence is not in itself a finding about the gene and the disease. The quoted sentences say what the papers report.
Alzheimer disease (2 papers, 2021 to 2024). A progressive, neurodegenerative disease characterized by loss of function and death of nerve cells in several areas of the brain leading to loss of cognitive function such as memory and language. "The down-regulated DEGs in NM versus NN were primarily focused on ribosome (about 26 DEGs, including RPL37A and RPL35), Alzheimer’s disease (about 20 DEGs, including SNCA and COX8A), and retrograde endocannabinoid signaling (about 6 DEGs, such as NDUFA1 and GNG5)." (PMID 38660519, 2024). "The DEGs that were down-regulated in DM compared to NM were primarily related to the ribosome (about 23 DEGs, including RPL37A and RPS11), Alzheimer’s disease (about 19 DEGs, including APC2 and COX8A), and non-alcoholic fatty liver disease (about 11 DEGs, such as SNCA and COX8A)." (PMID 38660519, 2024).
breast carcinoma (2 papers, 2024 to 2025). "Furthermore, cytochrome c oxidase subunit 8A was found to be causally associated with breast cancer as a protective factor (IVW, p=0.037, OR = 0.900, 95% CI: 0.815–0.994)." (PMID 39742384, 2024). "Conversely, 39S ribosomal protein L32, ADP-ribose pyrophosphatase, and cytochrome c oxidase subunit 8A were identified as protective factors against breast cancer in this population." (PMID 39742384, 2024). "Others, including Cox8a, Ndufb8, and Atad1, which are the genes involved in oxidative phosphorylation pathway, also exhibited an opposite regulation by Srsf3 KO in our Erbb2 breast cancer and DEN-induced liver cancer." (PMID 40568073, 2025). "In addition, cytochrome c oxidase subunit 8A and ADP-ribose pyrophosphatase were found to be protective factors against breast cancer in European populations." (PMID 39742384, 2024).
cholangiocarcinoma (2 papers, 2022 to 2024). A carcinoma that arises from the intrahepatic biliary tree (intrahepatic cholangiocarcinoma) or from the junction, or adjacent to the junction, of the right and left hepatic ducts (hilar cholangiocarcinoma). "To determine the role of 4-key-genes in cholangiocarcinoma CSCs, we first knocked down SDHAF2, MRPS34, MRPL11 and COX8A in HCCC9810 cell and overexpressed them in RBE cell, respectively." (PMID 35841118, 2022). "In our study, we demonstrated that CSCs in cholangiocarcinoma have different methionine metabolic features, and 4-key-genes (SDHAF2, MRPS34, MRPL11 and COX8A) could promote ICC stemness in a MAT2A-dependent manner." (PMID 35841118, 2022).
Leigh syndrome (2 papers, 2017 to 2020). "One patient with variants in COX8A has been reported to induce Leigh syndrome, but why the other 24 assembly/ancillary proteins have not been shown to produce this disease is unclear." (PMID 33426505, 2020).
epilepsy (1 paper, 2024). A brain disorder characterized by episodes of abnormally increased neuronal discharge resulting in transient episodes of sensory or motor neurological dysfunction, or psychic dysfunction. "Previous study shows that COX8A may lead to a number of inherited disorders such as Leigh‐like syndrome and epilepsy." (PMID 39206872, 2024).
lymph node metastasis (1 paper, 2022). "Since multivariate analysis suggested that CA19-9, tumor size, lymph node metastasis, SDHAF2, MRPL11 and COX8A are independent factors for OS of ICC patients with adjuvant TACE, a nomogram that included all these risk factors was constructed (C-index: 0.85, 0.81–0.89)." (PMID 35841118, 2022). "In addition, multivariate analysis showed that SDHAF2, MRPL11, COX8A, serum carbohydrate antigen 19-9 (CA19-9), tumor size and lymph node metastasis are independent factors for overall survival (OS) of ICC patients with adjuvant TACE." (PMID 35841118, 2022).
multiple myeloma (1 paper, 2024). "In the application of DrugFormer to the scRNA‐seq data of multiple myeloma, we unveiled a specific cancer cell state exhibiting stronger drug resistance while presenting elevated expressions of FEN1, RBX1, and COX8A." (PMID 39206872, 2024).
neuroblastoma (1 paper, 2020). Neuroblastoma (NB) is the most common solid, extracranial childhood tumor. "The specific nuclear-encoded mitochondrial genes in rhabdomyosarcoma were different from those enriched in neuroblastoma signature 18-positive samples, except for COX8A." (PMID 33056981, 2020).
Sepsis (1 paper, 2025). Sepsis is defined as life-threatening organ dysfunction caused by a dysregulated host response to infection. "Using single‐nucleus RNA sequencing data from an in vivo mouse model of sepsis, tissue‐independent down‐regulation and tissue‐specific differences of serine and energy‐related genes including key module roles for the mitochondria‐linked genes, Cox4i1, Cox8a, and Ndufa4 are identified." (PMID 40411399, 2025).
T-cell lymphomas (1 paper, 2015). "The most significantly mutated genes in Gr T-cell lymphomas are PSMA1, the cytochrome C oxidase subunit COX8A, and leukotriene A4 hydrolase (LTA4H)." (PMID 26377837, 2015).
tumor (28 papers, 2001 to 2025). "Additionally, studies suggest that high expressions of CYFRA 21-1 and IL-6 in tumor tissue, IL-17 surrounding tumor cells, and the genes SDHAF2, MRPS34, MRPL11, and COX8A in cancer stem cells are associated with a poor prognosis, thus offering novel prognostic avenues for exploration." (PMID 39170710, 2024).
cancer (7 papers, 2011 to 2024). A tumor composed of atypical neoplastic, often pleomorphic cells that invade other tissues. "Specifically, for COX8A, such association patterns were also observed in some other cancer types of TCGA patients, including ACC, LAML, LIHC, and LUAD." (PMID 39206872, 2024). "In addition, among the TCGA‐MM patients, high expressions of either FEN1, RBX1, and COX8A were significantly associated with poor overall survival and cancer‐specific survival." (PMID 39206872, 2024). "Possible mechanisms of drug resistance may involve the increase in chromosome copy number leading to upregulation of COX8A gene expression, thereby enhancing energy support, promoting cancer cell proliferation, and contributing to drug resistance." (PMID 39206872, 2024). "Furthermore, DrugFormer identifies potential therapeutic targets, such as COX8A, for overcoming drug resistance across different cancer types." (PMID 39206872, 2024).
infection (3 papers, 2013 to 2023). The state of being infected such as from the introduction of a foreign agent such as serum, vaccine, antigenic substance or organism. "Neurons were labeled with the mitochondrial marker cox8a-mscarlet (red) by infection with lentivirus under a neuron-specific synapsin promotor." (PMID 36834581, 2023).
neurodegenerative disease (1 paper, 2023). A disorder of the central nervous system characterized by gradual and progressive loss of neural tissue and neurologic function. "Ultimately, the temporal dynamics of the expression profiles of genes associated with neurodegenerative diseases, such as Ndufa2, Ndufb6, Snca, Ndufb8 and Cox8a, were characterized by trending." (PMID 37834317, 2023).
COX8A also shares sentences with these, for which no sentence is quoted: glioblastoma (22 papers); glioma (10); hemophilia (6); hemophilia A (6); ovarian carcinoma (2); astrocytoma (1); atherosclerosis (1); atrial fibrillation (1); Atypical Meningioma (1); Autoimmunity (1); benign meningioma (1); benign tumors (1); bleeding disorders (1); brain tumor (1); colorectal cancer (1); COVID-19 (1); deep venous thrombosis (1); factor deficiency (1); intrahepatic cholangiocarcinoma (1); Leukoencephalopathy (1); liver cancer (1); lymphoma (1); meningeal tumors (1); meningioma (1); mucopolysaccharidoses (1); non-alcoholic fatty liver disease (1); Ovarian Failure (1); Parkinson disease (1); prostate carcinoma (1); rhabdomyosarcoma (1).
A further 5 diseases each share a sentence with COX8A in 1 paper.